HNRNPD (heterogeneous nuclear ribonucleoprotein D)
Description:
Binds with high affinity to RNA molecules that contain AU-rich elements (AREs) found within the 3'-UTR of many proto-oncogenes and cytokine mRNAs. Also binds to double- and single-stranded DNA sequences in a specific manner and functions a transcription factor. Each of the RNA-binding domains specifically can bind solely to a single-stranded non-monotonous 5'-UUAG-3' sequence and also weaker to the single-stranded 5'-TTAGGG-3' telomeric DNA repeat. Binds RNA oligonucleotides with 5'-UUAGGG-3' repeats more tightly than the telomeric single-stranded DNA 5'-TTAGGG-3' repeats. Binding of RRM1 to DNA inhibits the formation of DNA quadruplex structure which may play a role in telomere elongation. May be involved in translationally coupled mRNA turnover. Implicated with other RNA-binding proteins in the cytoplasmic deadenylation/translational and decay interplay of the FOS mRNA mediated by the major coding-region determinant of instability (mCRD) domain. May play a role in the regulation of the rhythmic expression of circadian clock core genes. Directly binds to the 3'UTR of CRY1 mRNA and induces CRY1 rhythmic translation. May also be involved in the regulation of PER2 translation.
Synonyms: AUF1; HNRPD; AUF1A; P37; hnRNPD0
Tractability: PROTAC: UniProt records ubiquitination sites on it; ubiquitination databases record sites on it; its protein half-life has been measured.
Gene: Protein-coding gene on chromosome 4 (82,351,523 to 82,374,543, reverse strand). Ensembl gene ENSG00000138668.
Subcellular location: Nucleus; Cytoplasm
Subcellular location (Human Protein Atlas): Nucleoplasm
Pathways (Reactome):
Metabolism of RNA: AUF1 (hnRNP D0) binds and destabilizes mRNA; Processing of Capped Intron-Containing Pre-mRNA; mRNA Polyadenylation; mRNA Splicing - Major Pathway
Disease: Dengue Virus Genome Translation and Replication; Dengue Virus-Host Interactions
Gene Ontology:
Molecular function: protein binding; RNA binding; telomeric DNA binding; chromatin binding; histone deacetylase binding; minor groove of adenine-thymine-rich DNA binding; mRNA 3'-UTR AU-rich region binding; mRNA binding; nucleic acid binding
Biological process: circadian regulation of translation; CRD-mediated mRNA stabilization; negative regulation of nuclear-transcribed mRNA catabolic process, deadenylation-dependent decay; positive regulation of cytoplasmic translation; positive regulation of translation; regulation of circadian rhythm; positive regulation of DNA-templated transcription; positive regulation of telomere capping; positive regulation of telomere maintenance via telomerase; regulation of DNA-templated transcription; regulation of gene expression; RNA catabolic process; RNA processing; 3'-UTR-mediated mRNA destabilization; cellular response to amino acid stimulus; cellular response to estradiol stimulus; cellular response to nitric oxide; cellular response to putrescine; cerebellum development; hepatocyte dedifferentiation; liver development; negative regulation of gene expression; positive regulation of gene expression; regulation of mRNA stability; response to calcium ion; and 4 more
Cellular component: cytosol; mCRD-mediated mRNA stability complex; nucleoplasm; ribonucleoprotein complex; chromatin; nucleus; cytoplasm; glutamatergic synapse; postsynaptic density
Genetic constraint (gnomAD): Loss-of-function variants: 2 observed, 28.33 expected, observed/expected ratio (o/e) 0.0706, 90% interval 0.028 to 0.22. The upper end of that interval is the gene's LOEUF score, 0.22, which puts it in group 1 of 6, group 1 being the genes least tolerant of losing a copy. Missense variants: 240 observed, 364.2 expected, observed/expected ratio (o/e) 0.66, 90% interval 0.59 to 0.73. Synonymous variants: 158 observed, 139.91 expected, observed/expected ratio (o/e) 1.13, 90% interval 0.99 to 1.29.
Gene-disease validity (ClinGen):
ClinGen rates the evidence that HNRNPD causes each of these diseases.
complex neurodevelopmental disorder (autosomal dominant): Definitive. A disorder that involves more than one phenotype associated with the central nervous system, including but not limited to intellectual disability, autism, and seizures (epilepsy).
Homologues: Orthologues: chimpanzee HNRNPD (100% identical), macaque HNRNPD (100% identical), dog HNRNPD (99% identical), pig HNRNPD (98% identical), mouse Hnrnpd (97% identical), rat Hnrnpd (96% identical), rabbit HNRNPD (79% identical), guinea pig HNRNPD (75% identical), zebrafish hnrnpd (73% identical), tropical clawed frog hnrnpd (70% identical). Paralogues in human: HNRNPAB (60% identical), HNRNPDL (57% identical), HNRNPA3 (33% identical), HNRNPA1 (32% identical), MSI2 (31% identical), HNRNPA1L3 (31% identical), HNRNPA1L2 (30% identical), MSI1 (30% identical), HNRNPA2B1 (30% identical), DAZAP1 (27% identical), RBM19 (26% identical), HNRNPA0 (26% identical), and 24 more.
Diseases named in the same sentence as HNRNPD in open-access papers:
HNRNPD is named in the same sentence as 93 diseases in open-access papers, as found by Europe PMC text mining. Sharing a sentence is not in itself a finding about the gene and the disease. The quoted sentences say what the papers report.
breast carcinoma (26 papers, 2012 to 2025). "Elevated hnRNPD promoter activity has also been reported in breast cancer cells." (PMID 35396527, 2022). "lncRNA AFAP1-AS1 interacts with HNRNPD, promotes the translation of ERBB2, and induces drug resistance in breast cancer." (PMID 36127734, 2022). "Additionally, a separate investigation revealed that the interaction between lncRNA THOR and hnRNPD led to hnRNPD stabilization and activation of the PI3K/AKT pathway, thereby facilitating the progression of breast cancer." (PMID 39350250, 2024).
colorectal cancer (11 papers, 2019 to 2024). A primary or metastatic malignant neoplasm that affects the colon or rectum. "In colorectal cancer, HNRNPD interacts with LINC01354 and contributes to proliferation and metastasis through the activation of the Wnt/β-catenin signaling pathway." (PMID 33767152, 2021).
colon cancer (8 papers, 2019 to 2024). "In colon cancer, HNRNPD reduces ATX mRNA stability by recognizing the AU element in its 3′UTR and further promotes the migration of colon cancer cells." (PMID 33542193, 2021).
lung carcinoma (7 papers, 2013 to 2025). "The TCGA database and immunohistochemical results showed that HNRNPD was highly expressed in lung cancer tissues and was highly consistent with NR2F6 expression in these tissues." (PMID 36119482, 2022). "The TCGA database results indicated that the expression level of HNRNPD in lung cancer tissues was higher than that in para-carcinoma tissues." (PMID 36119482, 2022). "The study also found that HNRNPD was highly expressed in lung cancer tissues and that its high expression level was highly consistent with the expression distribution of NR2F6." (PMID 36119482, 2022). "Meanwhile, the knockdown of HNRNPD can inhibit the proliferation of lung cancer cells and glioma cells." (PMID 36359113, 2022). "In this support, interaction of hnRNPK, hnRNPC, hnRNPL and hnRNPA2/B1 with hnRNPD in cervical and lung cancer cells has been reported earlier." (PMID 26318153, 2015). "Finally, the expression of heterogeneous nuclear ribonucleoprotein D (HNRNPD) in lung cancer tissue was analyzed using the TCGA database and immunohistochemistry." (PMID 36119482, 2022). "Knockdown of HNRNPD also inhibited the proliferation of lung cancer cells." (PMID 36119482, 2022). "NR2F6 may interact with HNRNPD to jointly regulate the progression of lung cancer, and this conclusion provides a new experimental basis for the study of the molecular targeted therapy of NSCLC." (PMID 36119482, 2022). "Furthermore, the TCGA database and immunohistochemical results showed that HNRNPD was highly expressed in lung cancer tissues and was highly consistent with NR2F6 expression in these tissues." (PMID 36119482, 2022). "Furthermore, it was found that the knockdown of HNRNPD can inhibit the proliferation of H460 lung cancer cells, and the interaction between NR2F6 and HNRNPD-coded proteins was confirmed by IP." (PMID 36119482, 2022). "The mass spectrometry analysis results revealed that 28 proteins interacted with NR2F6, from which the key protein that could promote the progression of lung cancer—HNRNPD—was screened out." (PMID 36119482, 2022). "As the results showed that the knockdown of NR2F6 could inhibit the proliferation of lung cancer cells, the effect of the knockdown of HNRNPD on the proliferation of lung cancer cells was further investigated." (PMID 36119482, 2022). "HNRNPD and its similar gene HNRNPDL have been reported to be strongly upregulated in various cancers, including lung cancer, and play key roles in inducing tumour growth and metastasis, while TMEM150C is not well studied in cancer biology." (PMID 39909829, 2025). "The HNRNPA2B1 levels were positively associated with TARDBP (R = 0.83), DHX9 (R = 0.73), HNRNPR (R = 0.77), SRSF1 (R = 0.79), HNRNPD (R = 0.75), and HNRNPM (R = 0.78) genes in lung cancer (all P < 0.001)." (PMID 35529270, 2022). "The impact of HNRNPD knockdown on the proliferation capacity of lung cancer cells was verified at cell level, and the relationship between NR2F6 and HNRNPD was verified by co-immunoprecipitation." (PMID 36119482, 2022). "In order to study the roles of HNRNPD and NR2F6 and their correlation in lung cancer, the TCGA database and immunohistochemical analysis were further used for verification." (PMID 36119482, 2022). "Lung cancer tissue sections used as positive controls showed strong nuclear hnRNPD expression, while no immunostaining was observed in tissue sections used as negative controls where the primary antibody was replaced by isotype specific IgG." (PMID 26318153, 2015).
thyroid cancer (7 papers, 2011 to 2021). "In thyroid cancer, cytoplasmic hnRNPD interacts with mRNAs encoding cyclins (A1, B1, D1 and E1) and cyclin-dependent kinase inhibitors." (PMID 26318153, 2015). "Thyroid carcinoma may recruit cytoplasmic hnRNPD to disturb the stability of mRNAs encoding cyclin-dependent kinase inhibitors, leading to uncontrolled growth and progression of tumor cells." (PMID 26805816, 2016).
glioma (5 papers, 2016 to 2022). A benign or malignant brain and spinal cord tumor that arises from glial cells (astrocytes, oligodendrocytes, ependymal cells). "Compared with NBTs, the expression of HNRNPD in glioma tissues significantly increased with the pathological grade." (PMID 33542193, 2021). "We found that compared with HNRNPD(−)-NC group, the proliferation, migration, invasion, and VM formation ability of glioma cells in HNRNPD(−) group were significantly reduced." (PMID 33542193, 2021). "Our study confirmed for the first time that HNRNPD and linc00707 are highly expressed in glioma tissues and cells, while ZHX2 and miR-651-3p are low expressed." (PMID 33542193, 2021). "Our study found that HNRNPD was highly expressed in glioma tissues and cells, knockdown of HNRNPD significantly reduced the expression of MMP2, MMP9, and VE-cadherin in U87 and U251 cells, further inhibited the VM formation." (PMID 33542193, 2021). "Further, western blot was used to detect the changes of the expression of VM formation-related proteins MMP2, MMP9, and VE-cadherin in glioma cells after HNRNPD knockdown, we found that compared with HNRNPD(−)-NC group, the expression of the proteins decreased significantly in HNRNPD(−) group." (PMID 33542193, 2021). "The expression levels of ZHX2 and miR-651–3p were remarkedly reduced, while HNRNPD, linc00707, and specific protein 2 (SP2) expression were remarkedly increased in glioma." (PMID 36232466, 2022). "In glioma cells, it has been reported that ZHX2 interacts with HNRNPD and further regulates vasculogenic mimicry (VM) formation through the linc00707/miR-651–3p/SP2 pathway." (PMID 36232466, 2022). "Knockdown of HNRNPD, linc00707, and overexpression of ZHX2, miR-651-3p significantly inhibit the VM formation ability of glioma cells." (PMID 33542193, 2021). "In this study, we first identified the endogenous expressions of HNRNPD, ZHX2, linc00707, miR-651-3p, and SP2 in glioma tissues and cells." (PMID 33542193, 2021). "The nude mouse xenograft model was used to further study the effects of HNRNPD, ZHX2, and linc00707 on the occurrence and development of glioma." (PMID 33542193, 2021). "HNRNPD, linc00707, and SP2 knockdown or ZHX2 and miR-651-3p overexpression suppressed glioma cells proliferation, migration, and invasion and vasculogenic mimicry (VM) formation." (PMID 33542193, 2021). "Moreover, increasing the ZHX2 and miR-651–3p expression or decreasing the expression of HNRNPD, linc00707, and SP2 suppressed glioma cells’ proliferation, migration, invasion, and VM formation." (PMID 36232466, 2022). "Meanwhile, we discovered that compared with knockdown of HNRNPD or overexpression of ZHX2 alone, the combination of the two could significantly inhibit the VM formation of glioma cells." (PMID 33542193, 2021). "The proliferation, migration, invasion, and VM formation ability of glioma cells in HNRNPD(−) + ZHX2(+)-NC group, HNRNPD(–)-NC + ZHX2(+) group, and HNRNPD(−) + ZHX2(+) group were significantly decreased, among which the HNRNPD(−) + ZHX2(+) group was the most significant." (PMID 33542193, 2021). "In the present study, HNRNPD, linc00707, and specific protein 2 (SP2) were highly expressed, while zinc fingers and homeboxes 2 (ZHX2) and miR-651-3p were remarkedly downregulated in glioma tissues and cells." (PMID 33542193, 2021).
oral squamous cell carcinoma (5 papers, 2020 to 2023). "We previously demonstrated a strong association of hnRNPD over expression with poor outcome in Oral Squamous Cell Carcinoma (OSCC)." (PMID 35396527, 2022). "The heterogeneous nuclear ribonucleoprotein D (hnRNPD) serves as a prognostic marker for oral squamous cell carcinoma (OSCC)." (PMID 35741145, 2022). "The finding of this study unearths almost comparable sensitivity of p40 and hnRNPD in diagnosing oral squamous cell carcinoma." (PMID 35741145, 2022). "Oral squamous cell carcinoma patients with increased HNRNPD expression significantly correlated with shorter recurrence‐free survival." (PMID 32915499, 2020). "However, in the case of oral squamous cell carcinoma specimens, a total of 38 cases out of 46 (82.60%) displayed positive nuclear staining for hnRNPD in basal and parabasal cells." (PMID 35741145, 2022).
cervical carcinoma (4 papers, 2015 to 2026). A carcinoma arising from either the exocervical squamous epithelium or the endocervical glandular epithelium. "The expression of the HPV16 E7 oncoprotein is enhanced upon knockdown of HNRNPD in HPV16-driven cervical cancer cells, indicating a crucial role of HNRNPD in the development of HPV-associated cancers." (PMID 39180763, 2024).
liver cancer (4 papers, 2018 to 2024). An epithelial or non-epithelial malignant neoplasm that arises from the liver. "HNRNPD was significantly upregulated in 13% of the tumors, consistent with other reports of its upregulation in esophageal, breast, skin, thyroid and liver cancers." (PMID 32452829, 2020).
melanoma (3 papers, 2015 to 2022). A malignant, usually aggressive tumor composed of atypical, neoplastic melanocytes. "Stimulation of melanoma cells and monocytes by lipopolysaccharide resulted in cytoplasmic translocation of hnRNPD from nucleus and reduced levels of IL-6, IL-10 and TNF-α following activation of MKP-1 (MAPK phosphatase-1)." (PMID 26318153, 2015).
sarcoma (3 papers, 2014 to 2021). A usually aggressive malignant neoplasm of the soft tissue or bone. "We previously reported that the G4 structure of a telomere DNA was retained on binding of fused in sarcoma (FUS), while it was destroyed on binding of heterogeneous nuclear ribonucleoprotein D0 (hnRNPD0)." (PMID 33801762, 2021).
bladder cancer (2 papers, 2019 to 2023). "For example, the ATG7 gene, which is overexpressed in invasive bladder cancer tissue, can promote autophagic degradation of the HNRNPD (ARE/poly(U)-binding/degradation factor 1) protein, which, in turn, increases ARHGDIB mRNA stability and bladder cancer cell invasion." (PMID 36875752, 2023).
Crohn disease (2 papers, 2019 to 2022). A gastrointestinal disorder characterized by chronic inflammation involving all layers of the intestinal wall, noncaseating granulomas affecting the intestinal wall and regional lymph nodes, and transmural fibrosis. "Moreover, a connection between mutations in the human hnRNPD gene and Crohn’s Disease has been revealed from studies on monozygotic twins." (PMID 35222366, 2022).
gastric cancer (2 papers, 2022 to 2025). A primary or metastatic malignant neoplasm involving the stomach. "5′tRNA derivative tRF-Tyr competitively binds hnRNPD to modulate the c-Myc/Bcl2/Bax pathway, suppressing gastric cancer." (PMID 40565315, 2025). "The 5′tRNA derivative tRF-Tyr competitively binds hnRNPD to modulate the c-Myc/Bcl2/Bax pathway, suppressing gastric cancer." (PMID 40565315, 2025).
lymphoma (2 papers, 2021 to 2023). A malignant (clonal) proliferation of B- lymphocytes or T- lymphocytes which involves the lymph nodes, bone marrow and/or extranodal sites. "Our findings indicated that HNRNPD and YBX1 are required for TCLlnc1-mediated regulation of TGF-β signaling pathway, as well as T-lymphoma cell proliferation and migration." (PMID 33767152, 2021). "TCLlnc1/HNRNPD/YBX1 complex upregulated transcription of TGFB2 and TGFBR1 genes, activated the tumor growth factor-β signaling pathway, resulting in lymphoma progression, and might be a potential target in PTCL." (PMID 33767152, 2021).